PRL (prolactin)
Diseases named in the same sentence as PRL in open-access papers (continued):
Sharing a sentence is not in itself a finding about the gene and the disease.
schizophrenia (continued). "The biomarkers identification showed specific and sensitive results for schizophrenia, where two proteins (PRL and MRC2) produced adequate results." (PMID 35546954, 2022). "Previous studies have also shown significantly increased HC and PRL levels in antipsychotic-naïve schizophrenia and related disorders." (PMID 34305687, 2021). "Sexual dysfunction was significantly related to higher prolactin levels in olanzapine-treated patients with schizophrenia, with significant differences between the sexes." (PMID 34421613, 2021). "Given that prolactin is under negative control by dopamine and positive control by serotonin, olanzapine has been reported to induce moderately elevated prolactin levels in patients with schizophrenia." (PMID 34421613, 2021). "Haloperidol, known as the first-line treatment for schizophrenia, has unwanted effects which include increases in prolactin levels and extrapyramidal symptoms." (PMID 34526046, 2021). "Cognitive deficit in schizophrenia has been related to an increase in inflammatory cytokines, to an imbalance in hormones such as cortisol and prolactin, in neurotrophic factors such as BDNF and in neurotransmitters such as GABA and glutamate." (PMID 34576069, 2021). "Prolactin levels, metabolic parameters, and sexual function in olanzapine-treated patients with schizophrenia should be monitored regularly." (PMID 34421613, 2021). "Rankings of adjunctive aripiprazole, metformin and PGD in reducing prolactin levels in schizophrenia." (PMID 34658963, 2021). "The aim of the study was to assess the relationship between prolactin levels and sexual dysfunction in patients with schizophrenia who use olanzapine medication." (PMID 34421613, 2021). "First-episode drug-naïve male schizophrenia patients have serum PRL levels 3 times higher than healthy male controls." (PMID 33315097, 2021). "It has been observed that in antipsychotic-naive schizophrenia patients, higher levels of prolactin are related to poorer cognitive performance." (PMID 34576069, 2021). "This study aimed to evaluate the relationship between an abnormally low PRL and a rebound in psychotic symptoms after switching to aripiprazole in patients with schizophrenia." (PMID 33228575, 2020). "Intriguingly, the PRL of schizophrenia outpatients became lower right before relapse compared to those during the stable period." (PMID 33228575, 2020). "In schizophrenia patients with sexual dysfunction, the treatment usually begins with PRL-sparing antipsychotics, switching to quetiapine in a second phase." (PMID 32373066, 2020). "Case reports and retrospective studies among adult schizophrenia patients receiving aripiprazole also showed abnormally low PRL, with varying thresholds." (PMID 33228575, 2020). "But TRACP-5b (r = − 0.352, P < 0.05), PRL (r = − 0.519, P < 0.01), duration of illness (r = − 0.353, P < 0.05) were negatively correlated with BMD in male schizophrenia with elevated PRL levels." (PMID 32788631, 2020). "To fill in the gap in the literature, we turned to a trial of schizophrenia patients with repeated measurements for PRL and positive symptoms after switching to aripiprazole." (PMID 33228575, 2020). "Un-medicated women with schizophrenia appear to have lower mean daily prolactin levels than healthy controls." (PMID 32017792, 2020). "An abnormally low prolactin level after switching to aripiprazole in schizophrenia patients was a potential warning sign of a psychotic rebound." (PMID 33228575, 2020). "Here, we found that dietary intake of 0.1% GF food pellets during pregnancy and lactation prevented ASD‐ and schizophrenia‐like behavioral abnormalities and reduction of PV immunoreactivity in the PrL of the mPFC in offspring after MIA." (PMID 32463181, 2020). "In contrast to lithium, it is widely known that many antipsychotic medications were reported to strongly increase prolactin levels in BPD patients in addition to schizophrenia patients." (PMID 31297456, 2019).
schizophrenia (continued). "A Bayesian network meta-analysis was used to compare changes in prolactin levels in pediatric patients diagnosed with schizophrenia or schizophrenia spectrum disorders treated with second-generation antipsychotics (SGAs)." (PMID 29805808, 2018). "In a review on the literature of the relationship between PRL and schizophrenia Rajkumar R.P. recommended a reappraisal of the role of prolactin in the various stage of schizophrenia, particularly with regard to its onset." (PMID 30068291, 2018). "This study found that the serum prolactin level increased in some patients with schizophrenia who were treated with antipsychotics." (PMID 29209406, 2017). "From these results, we suggest that clinicians should monitor the level of prolactin and cognitive function in patients with schizophrenia in future studies on managing of lower-limb fractures." (PMID 28320371, 2017). "Neuroendocrine biomarkers, such as cortisol, insulin, leptin, pro-opiomelanocortin, prolactin and growth hormone were similarly altered in the brain and in the blood in patients with schizophrenia." (PMID 28358316, 2017). "Women with schizophrenia had a significantly higher level of testosterone and lower level of prolactin compared to healthy women." (PMID 27293968, 2016). "By LC-MSE, prolactin was significantly lower, by approximately 35% in pituitary from chronically medicated individuals with schizophrenia, suggesting that despite antipsychotic medication, prolactin production was suppressed by elevated dopamine." (PMID 26909022, 2016). "Plasma levels of testosterone, DHEA, cortisol, and prolactin hormones in normal controls and patients with schizophrenia were compared using multivariate analysis of variance (MANOVA)." (PMID 27293968, 2016). "The purpose of the present study was to compare plasma neurosteroid (cortisol, testosterone, dehydroepiandrosterone (DHEA)), and prolactin levels in patients with schizophrenia and healthy individuals." (PMID 27293968, 2016). "This review was designed to evaluate the frequency of prolactin-related adverse events and to consolidate/quantify differences in prolactin level changes between antipsychotics in pediatric patients with schizophrenia and schizophrenia spectrum disorders." (PMID 27825323, 2016). "While this review was focused on pediatric patients with schizophrenia, in order to present outcomes for a well-defined clinical area, it must also be recognized that the potential for treatment-related prolactin elevation is not limited to this population." (PMID 27825323, 2016). "A 1992 study of schizophrenia patients found that serum prolactin increased more markedly in female patients following the commencement of neuroleptic medications, despite the female patients receiving lower doses of treatment." (PMID 27825323, 2016). "Lurasidone's combination of efficacy in schizophrenia and bipolar depression with minimal metabolic disturbance and little effect on movement disorders and prolactin represents a potentially important clinical advance." (PMID 26755968, 2015). "Our study has found decreased estradiol levels in men with schizophrenia treated with clozapine and risperidone, while prolactin levels were increased only in risperidone treated group." (PMID 26664488, 2015). "This systematic review will evaluate prolactin-based adverse events of first- and second-generation antipsychotics in the pediatric population with schizophrenia and schizophrenia spectrum disorders." (PMID 25312992, 2014). "A review of the literature on prolactin and schizophrenia suggests that the relationship between them is complex and not confined to the adverse effects of antipsychotics." (PMID 24800074, 2014). "Only one study has examined the effects of stress in this patient population and found a significantly greater increase in stress-stimulated prolactin in schizophrenia." (PMID 24800074, 2014).
schizophrenia (continued). "Given its relationship with parental bonding, an effect of prolactin on social cognition and behavior—both of which are significantly impaired in schizophrenia—is plausible." (PMID 24800074, 2014). "Third, provocation studies provide further support for the idea of blunted or lowered prolactin secretion in patients with “positive” schizophrenia." (PMID 24800074, 2014). "The possibility that schizophrenia has a unique circadian profile of prolactin and sleep changes, distinct from those seen in depression, must be seriously considered but requires further replication in larger samples using a consistent study protocol." (PMID 24800074, 2014). "A blunted prolactin response to pharmacological challenge in schizophrenia is documented across various classes of agents—adrenergic, serotonergic, and dopaminergic." (PMID 24800074, 2014). "A tentative model, which synthesizes these findings and argues for a significant role for prolactin in the development of schizophrenia, is outlined." (PMID 24800074, 2014). "Secretion of the anterior pituitary hormone prolactin can be significantly increased by antipsychotic drugs, leading to a range of adverse effects in patients with schizophrenia." (PMID 24800074, 2014). "In this paper, a selective review of all relevant studies pertaining to prolactin and schizophrenia, including challenge and provocation studies, is presented." (PMID 24800074, 2014). "A variety of drugs—hormones, adrenergic agonists, serotonergic agonists, and dopamine antagonists—have been used to study prolactin release in patients with schizophrenia." (PMID 24800074, 2014). "In an open label study testing the effectiveness of cabergoline, an ergot derivative and full dopamine agonist, to improve prolactin related side effects, 11/19 (58%) male and female participants with schizophrenia had improvement in their symptoms." (PMID 23968123, 2013). "We also measured the prolactin/growth hormone and insulin/growth hormone ratios as these are known to be affected in insulin resistant states, which can occur in some schizophrenia patients." (PMID 24244349, 2013). "In this study, the percentage of schizophrenia patients who had an abnormal prolactin levels (>25 ng/ml) at endpoint was significantly higher in the risperidone group (93%) than in the aripiprazole group (5%)." (PMID 23968123, 2013). "The use of antipsychotics in the men with schizophrenia must be considered carefully as a potential confound as prolactin-elevating antipsychotics have been shown to influence testosterone levels." (PMID 24204845, 2013). "The most common adverse events leading to discontinuation were worsening of schizophrenia or other psychosis (n = 5), movement disorder symptoms (n = 3), and elevations in prolactin level (n = 2)." (PMID 22903391, 2013). "This protein was decreased in female schizophrenia patients in parallel with increased free and total testosterone and differences in prolactin and growth hormone levels." (PMID 24244349, 2013). "Evidence from cross-sectional patient-based studies in drug naive schizophrenia patients suggests that high dopamine and subsequently low PRL concentrations are related to an increased T2DM risk, including insulin resistance and impaired fasting glucose." (PMID 23517652, 2013). "The significant risk factors for suicide behaviors were previous suicidality, depressive symptoms, prolactin-related adverse events, male gender and history of hospitalization for schizophrenia." (PMID 22812421, 2012). "The significant risk factors for suicide behaviors that were identified were: history of suicide attempts, male gender, depressive symptoms, history of hospitalization for schizophrenia and prolactin-related adverse events." (PMID 22812421, 2012). "We have also demonstrated that the levels of hormones such as insulin, cortisol, progestone, prolactin, growth hormone and chromogranin A are altered in the circulation of first onset schizophrenia patients compared to controls." (PMID 23118852, 2012).
schizophrenia (continued). "Shrivastava and Tamhane studied serum prolactin level in 20 male and 11 female drug naive schizophrenia patients." (PMID 21836670, 2010). "In patients with schizophrenia, amantadine decreases prolactin levels secondary to treatment with an antipsychotic." (PMID 17262163, 2006). "However, very few studies have investigated sex-specific differences in the prevalence of PRL disturbances in first-episode patients with schizophrenia." (PMID 40971478, 2025). "However, birth rates in women with schizophrenia are increasing, probably due to both the use of antipsychotics that have less effect on prolactin and the effectiveness of current treatments for schizophrenia." (PMID 41008479, 2025). "It is noteworthy that the decrease in serum prolactin abnormalities induced by aripiprazole may serve as a biomarker for the rebound of positive symptoms in patients with schizophrenia." (PMID 38505795, 2024). "Elevated prolactin levels or HPRL was common in schizophrenia patients receiving antipsychotics, which may raise the prolactin level by antagonizing the D2 receptor in the pituitary lactotroph cells." (PMID 39267697, 2024). "Currently, medications approved to treat schizophrenia often come with a range of side effects, including sedation/somnolence and agitation or insomnia, prolactin elevation and sexual dysfunction, neuromotor symptoms, and weight gain and metabolic disturbances." (PMID 39199294, 2024). "Indeed, concerns exist about BMD in patients with schizophrenia treated with prolactin-elevating medications, and this issue seems to be confirmed by our study." (PMID 39682653, 2024). "Previous research has highlighted variations in serum PRL secretion among individuals experiencing first-episode unmedicated schizophrenia, indicating that schizophrenia may entail anomalous regulation of PRL levels." (PMID 39267697, 2024). "Hence, aripiprazole treatment proves to be both efficient and safe for patients undergoing acute episode of schizophrenia, despite varying baseline PRL levels." (PMID 39267697, 2024). "Further, at baseline the patients with elevated PRL levels had less severe psychiatric symptoms than those with normal PRL levels, similar to the inverse relationship between basal PRL levels and the severity of positive symptoms found in patients with acute schizophrenia in a number of studies." (PMID 39267697, 2024). "Aripiprazole not only worsened the severity of index disturbances associated to metabolism in long-term hospitalized chronic schizophrenia patients with co-T2DM on metformin-based hypoglycemic medications but also failed to lower PRL levels." (PMID 36816406, 2023). "Other authors found increased PRL levels in patients with first-episode schizophrenia." (PMID 37047464, 2023). "Therefore, it has been postulated that monitoring prolactinemia is of great importance in women with schizophrenia who are treated with PRL-increasing antipsychotics." (PMID 36833950, 2023). "According to us, this may be the only study to date to clarify whether aripiprazole can reduce PRL levels in schizophrenia patients with co-T2DM." (PMID 36816406, 2023). "It was previously suggested that decreased levels of prolactin could worsen the onset of schizophrenia symptoms and has a probable role in severe depression development." (PMID 37252132, 2023). "In addition, the advantage of aripiprazole at the dose of <5 mg/day compared to higher doses suggests that higher doses are unnecessary to reduce the AP-induced prolactin level for schizophrenia." (PMID 34658963, 2021). "In conclusion, homocysteine and/or PRL levels may serve as candidate prognostic markers for schizophrenia." (PMID 33995058, 2021). "Other candidate genes, PRL-releasing hormone receptor (PRLRH), PRL receptor (PRLR), oxytocin (OXT), oxytocin receptor (OXTR), and NPY, may also correlate with the PRL pathway and contribute to schizophrenia and T2DM." (PMID 33315097, 2021).
schizophrenia (continued). "For all participants with schizophrenia, prolactin level (B = 0.012, p < 0.001), concomitant antidepressant (B = 0.460, p < 0.001), HOMA-IR (B = 0.018, p = 0.001), duration of illness (B = 0.007, p = 0.008), and female sex (B = 0.0.127, p = 0.013) were associated with sexual dysfunction." (PMID 34421613, 2021). "Blonanserin exerted the similar efficacy to risperidone in both positive and negative symptoms in schizophrenia with a lower risk of prolactin increase, weight gain, and orthostatic hypotension compared with risperidone." (PMID 31788985, 2020). "Importantly, the change in serum PRL levels and bone metabolism markers should be monitored closely by clinicians treating schizophrenia patients." (PMID 32788631, 2020). "Given the paucity of data, it is impossible to exactly determine if PRL and bone mass alterations are connected in schizophrenia patient, especially in the patients with higher PRL levels; therefore, more research is needed to determine if an actual interaction exists between the two." (PMID 32788631, 2020). "Hence, PRL and bone metabolism markers should be examined to monitor the bone health status of schizophrenia patients, especially those who are on antipsychotic drug regimens for an extended period, in order to better prevent osteoporosis and fractures." (PMID 32788631, 2020). "However, there is inconsistency among studies investigating the correlation between elevated PRL resulting from antipsychotic treatment and bone metabolism in schizophrenia patients." (PMID 32788631, 2020). "This study aimed to assess whether the aripiprazole-induced abnormally low prolactin level was a biomarker for subsequent rebound of positive symptoms in schizophrenia patients." (PMID 33228575, 2020). "In conclusion, our findings revealed that an abnormally low PRL after switching to aripiprazole in schizophrenia patients might be a potential warning sign of a rebound in psychotic symptoms." (PMID 33228575, 2020). "Blonanserin showed the similar efficacy to risperidone in both positive and negative symptoms in schizophrenia with a lower risk of prolactin increase, weight gain, and orthostatic hypotension compared with risperidone." (PMID 31788985, 2020). "Antipsychotic-induced weight gain, including as a consequence of increasing the level of prolactin, can be a particular problem of in schizophrenia treatment, often causing non-compliance and consequent relapse." (PMID 30967134, 2019). "Further replications trough longitudinal studies including larger samples would be needed to a better understanding of the relationship between schizophrenia spectrum psychosis, regulation of prolactin secretion and IR, according to different age of onset and different stage of disease." (PMID 30068291, 2018). "Some authors have identified variations in PRL secretion in drug-free patients, suggesting that schizophrenia itself may be characterized by an abnormal regulation of PRL levels." (PMID 30068291, 2018). "The cimetidine-induced increase in prolactin secretion in schizophrenia: effect of clozapine." (PMID 30093869, 2018). "In this context, NMA is a useful technique to compare the direct and indirect evidence available to assess the relative safety of SGAs in the treatment of pediatric patients diagnosed with schizophrenia and schizophrenia spectrum disorders, specifically regarding increased serum prolactin levels." (PMID 29805808, 2018). "An increased level of PRL triggers dopamine release by a feedback mechanism, therefore it is reasonable to infer that patients with schizophrenia may have an exaggerated PRL response to stress mediated by a dysfunction in dopaminergic transmission." (PMID 30068291, 2018). "Therefore, we conducted a network meta-analysis (NMA) to study the relative changes in serum prolactin levels in pediatric patients diagnosed with schizophrenia and schizophrenia spectrum disorders treated with SGAs." (PMID 29805808, 2018).